SIRT1 (sirtuin 1)
Diseases named in the same sentence as SIRT1 in open-access papers (continued):
Sharing a sentence is not in itself a finding about the gene and the disease.
infection (continued). "Pharmacologically inhibiting SIRT1 deacetylase activity in septic mice reverses monocyte immune tolerance, clears infection, rebalances glycolysis and glucose oxidation, resolves organ dysfunction, and prevents most septic deaths." (PMID 30069485, 2018). "In HSV-1 infection, the activated AMPK/Sirt1 axis inhibits host-cell apoptosis during early-stage infection, which promotes viral latency and protects neurons." (PMID 30404221, 2018). "Sirt1 co-localized with S. Typhimurium containing vacuoles (SCV) at 1h post infection, which diminished at 4h." (PMID 28192515, 2017). "We also found that LKB1 and AMPK co-immunoprecipitated with Sirt1, yet the abundance of the proteins were markedly reduced at 4h post infection." (PMID 28192515, 2017). "We show here that S. Typhimurium markedly down-regulates Sirt1 expression commencing within 1h post infection." (PMID 28192515, 2017). "Immunoblot analysis of isolated S. Typhimurium-containing phagosomes revealed the presence of Sirt1 in phagosomes within 30min, which rapidly declined at later time points post infection." (PMID 28192515, 2017). "The activation of NF-κB is increased following infection and SIRT1 is known to deacetylate NF-κB thereby inhibiting its activity." (PMID 28533769, 2017). "In particular, AD transgenic mouse models displayed a strikingly reduced Aβ burden in the hippocampus and cortex when SIRT1 was chemical activated or overexpressed by lentiviral infection." (PMID 27209302, 2016). "Compared with the SIRT1-knocked down cells, the stable cells downregulated SIRT1 and Wnt signaling antagonists through RNAi vector co-infection and accumulated much less fat droplets, as determined by oil red O staining." (PMID 27776347, 2016). "We established SIRT1 depleted and control cells that stably express shRNA as a result of infection with a recombinant retrovirus." (PMID 25635860, 2015). "We established BJ/TERT cells that stably expressed SIRT1 as a result of infection with a recombinant retrovirus." (PMID 25635860, 2015). "Most importantly, a transient decrease in SIRT1 expression at the transcription and translational levels was observed both in vitro and in vivo infections." (PMID 25738568, 2015). "Nevertheless, the promiscuous relation of AMPK and SIRT1 appears to be cell specific and their putative role during infection remains elusive." (PMID 25738568, 2015). "The infection of mice with DN SIRT1-expressing adenovirus abrogated the protective effect of IFN-β on LPS-induced endotoxic or CLP-induced septic shock (middle and right)." (PMID 24573134, 2014). "In vivo treatment of interferon β protects against lethal endotoxic and septic shock, which is abrogated by infection with dominant negative SIRT1-expressing adenovirus." (PMID 24573134, 2014). "SIRT1 activating compound SRTAW04 significantly attenuates neuronal loss induced by MHV-A59 and RSA59 infection." (PMID 24383546, 2014). "Increased SIRT1 activity also increased the activity of oxidative stress enzymes such as catalase and peroxidase and decreased the levels of Nitric oxide and thus infection." (PMID 24950067, 2014). "Cell proliferation in either HCMV or mock infection remained unchanged with treatment of resveratrol or SIRT1 siRNA." (PMID 24376725, 2013). "To further evaluate the effect of SIRT1 on mitochondrial biogenesis, we determined the effect of overexpression of SIRT1 by adenovirus mediated infection of C2C12 cells, and electroporation of rat triceps muscle, with a SIRT1 gene construct." (PMID 23874150, 2013). "For example, infection decreases SIRT1 expression and activity and activation of SIRT1 exerts beneficial effects on endothelial cell dysfunction." (PMID 23132960, 2012).
infection (continued). "SIRT1 is a crucial regulator of metabolic processes in response to changes in nutrient availability, thereby controlling energy homeostasis and the metabolic state, and orchestrating immune and inflammatory responses during infection." (PMID 41263555, 2025). "Given that immune cells are crucial for managing immune‐related diseases, the interplay between SIRT1 and HIF‐1α metabolism is closely linked to various immune‐related conditions, including infections, tumors, allergic airway inflammation, and autoimmune diseases." (PMID 41416347, 2025). "Moreover, the infection increases the expression of sirtuin 1 (SIRT1), which inhibits EV-D68 replication in turn." (PMID 40006932, 2025). "In our study, we observed a significant upregulation of SIRT1 levels during EV-D68 infection." (PMID 40006932, 2025). "We proposed that the initially low cytoplasmic SIRT1 levels during early infection may limit its ability to counteract viral replication, potentially facilitating viral processes such as vesicular release." (PMID 40006932, 2025). "SIRT1 is critical for the activation of type I IFN expression during infection." (PMID 39487323, 2025). "Overall, the sirtuin-1 pathway appears to act against both infectious processes as well as AD pathogenesis and its downregulation may be a key step in infection exacerbated AD." (PMID 38770241, 2024). "Moreover, there was only a significant reduction in anti-inflammatory IL-10 production upon Sirt1 and Sirt3 knockdown at 2 hr and 20 hr post-infection." (PMID 39693143, 2024). "However, our in vivo findings in the murine model of infection show increased bacterial burden upon SIRT1 or SIRT3 inhibition." (PMID 39693143, 2024). "The Sirt1 expression level declined at later phases of infection." (PMID 39693143, 2024). "Further, we estimated the production of another pro-inflammatory cytokine, IL-1β at 20 hr post-infection under the knockdown condition of Sirt1 and Sirt3 and observed heightened IL-1β production under knockdown of Sirt1 and Sirt3 in comparison to the scrambled infected control." (PMID 39693143, 2024). "Upon infection by Cp, the SIRT1 pathway is reduced in macrophages." (PMID 38770241, 2024). "However, in murine model of infection, SIRT1 or SIRT3 inhibitor treatment led to increased organ burden and triggered bacterial dissemination." (PMID 39693143, 2024). "Lactate estimation assay in Sirt1 and Sirt3 knockdown condition revealed enhanced lactate production at 16 hr post-infection in comparison to the scrambled control, which further authenticates the increased host glycolysis upon Sirt1 and Sirt3 knockdown scenario." (PMID 39693143, 2024). "Interestingly, an antagonistic crosstalk between NF-κB and SIRT1 signaling pathways in regulating immune and inflammatory response to infection has been uncovered." (PMID 38041753, 2024). "Importantly, cART treatment only led to significant decreases in p16 and SIRT1 expression relative to chronic, untreated infection in the hippocampus, with significant increases relative to naïve animals in several brain regions." (PMID 39149452, 2024). "To evaluate the immune regulatory mechanism of SIRT1 in the S. Typhimurium (STM) infection scenario, we undertook SIRT1 immunoprecipitation in the infected RAW 264.7 macrophages at 16 hr post-infection alongside the uninfected macrophages and probed for NF-κB p65 interaction." (PMID 39693143, 2024). "Since the induction of ER stress, through either SIRT-1 depletion or TG treatment, attenuates EV-D68 egress, we asked whether EV-D68 infection induces ER stress." (PMID 37850626, 2023). "It will be interesting to examine whether other Betacoronaviruses alter the subcellular localization of SIRT-1 and whether SIRT-1 is important for their infection." (PMID 37850626, 2023). "We next sought to understand whether SIRT-1 modulates the infection of other medically important enteroviruses, including PV and CVB3." (PMID 37850626, 2023).
infection (continued). "Interestingly, for the extracellular vesicle fraction, we observed that SIRT-1 knockdown decreased the release of CD63-positive EVs during EV-D68 infection compared to the scramble control." (PMID 37850626, 2023). "Interestingly, EV71 has also been reported to induce SIRT-1 relocalization to the cytosol during infection." (PMID 37850626, 2023). "Enterovirus D68 (EV-D68) infection changes SIRT-1’s subcellular localization." (PMID 37850626, 2023). "To understand whether SIRT-1 translocation during EV-D68 infection is dependent on exportin-1, the major mammalian nuclear export protein, we pretreated H1HeLa cells with and without leptomycin-B, a specific exportin-1 inhibitor, followed by EV-D68 infection." (PMID 37850626, 2023). "From these observations, we propose a tentative conclusion, though debatable, that of the seven sirtuin proteins, SIRT1, 3, 5, and 7 perform a protective function against infections with MTB whereas, SIRT2, SIRT4 and SIRT6 interfere with macrophage pathways facilitating pathogen survival." (PMID 36993975, 2023). "After fully optimizing the infection conditions, it was found that shSIRT1#3 and shSIRT3#2 were the sequences with the best effects on gene knockdown among the three shRNA sequences targeting SIRT1 and SIRT3." (PMID 38012584, 2023). "Sirt1 inhibition is necessary to drive NF-κB-mediated HIV1 transcription during the early phase of infection, while Sirt1-dependent Tat deacetylation promotes its release from PCAF, freeing up Tat for binding to TAR, and thereby, initiating a new cycle of viral transcription." (PMID 37109478, 2023). "In addition, most studies have reported the SIRT1 regulation of innate and inflammatory responses in the context of infection; future studies are needed to clarify the exact function of SIRT1 in regulating adaptive immune responses to impact host defense." (PMID 36139497, 2022). "SIRT1, one of the most well-studied sirtuins, has become recognized as a critical modulator in the diverse aspects of host immune and inflammatory responses in the context of infection." (PMID 36139497, 2022). "RSV treatment increased the expression of SIRT1 and reversed the effect of mitochondrial dysfunction induced by infection of N. caninum tachyzoites, while Ex 527 further decreased SIRT1 expression and aggravated mitochondrial damage effects caused by N. cannum infection." (PMID 35915458, 2022). "Likewise, the inhibition of SIRT1 related to suppressed mTOR activation and resulted in reduced inflammation and damage in the lung after infection." (PMID 34952202, 2022). "The functions of SIRT1 include orchestrating immune, inflammatory, metabolic, and autophagic responses, all of which are required in establishing and controlling host defenses during infection." (PMID 36139497, 2022). "Finally, the possibility of using SIRT1 agonists or inhibitors in the control of infections should be investigated in experimental and clinical studies." (PMID 36139497, 2022). "In our study, SIRT1 mainly activated in jejunum and ileum during infection." (PMID 35571917, 2022). "In view of the vital physiological function of SIRT1 in the regulation of mitochondrial metabolism, future research should be focused on the molecular mechanisms by which SIRT1 functions in the immunometabolic remodeling required for host defenses during infection." (PMID 36139497, 2022). "Thus, we suggest that HIV virus, and infection itself, should affect in other ways the SIRT1 activity, besides its suppression by Tat-HIV protein." (PMID 32106282, 2020). "This highlights the possible involvement of SIRT1 and senescence-associated pathways in modulating SARS-CoV-2 pathogenesis in humans, thereby putting smokers/vapers at a higher risk of contracting an infection." (PMID 32528233, 2020). "We found that loss of SIRT1 or SIRT2 was not sufficient to block infection; however, sirtinol treatment of either mutant led to strong reductions in infection." (PMID 31289184, 2019).
infection (continued). "In addition, Ad-SIRT1 infection significantly decreased hepatocyte TG content under NEFA treatment conditions." (PMID 29207650, 2017). "In addition, we found that infection with Ad-SIRT1 prevented NEFA-mediated insulin signaling pathway impairment." (PMID 29207650, 2017). "Conversely, Sirt1 activators may potentially be useful for the control of inflammatory damage and control of pathogen spread during later stages of infections." (PMID 28018344, 2016). "At day 2 post-infection, we observed efficient knockdown of SIRT1." (PMID 27708228, 2016). "Infection of shSIRT1-KD drastically reduced SIRT1 protein levels in K562 cells." (PMID 26646449, 2016). "For example, Sirt1 inhibiting drugs could potentiate vaccine responses and improve outcomes in very early stages of infection when enhanced immunity is essential." (PMID 28018344, 2016). "Using Western blot analysis, we demonstrated that the infection of 3T3-L1 preadipocytes with the lentiviral construct containing shSirt1 results in undetectable levels of the SIRT1 protein compared with control cells (uninfected and shScramble-expressing 3T3-L1 cells)." (PMID 26655722, 2016). "As for bacterial infection, myeloid Sirt1 expression was shown to have little influence in Gram-negative toxin-induced shock or Gram-positive bacteremia, whereas ablation of Sirt2 profoundly changed the outcome of infection with L. monocytogenes." (PMID 26135889, 2015). "Infections performed in mice deficient in the myeloid lineage for AMPK or SIRT1 demonstrated that the absence of each protein led to a significantly decrease on the liver, bone marrow and spleen parasite burden." (PMID 25738568, 2015). "Ultimately, a definitive demonstration of the biological role of AMPK and SIRT1 proteins was provided by infection of WT, myeloid restricted (Mac)-AMPK KO and Mac-SIRT1 KO mice with L. infantum, with evaluation of the parasite load in the spleen, liver and bone marrow 10 days post-infection." (PMID 25738568, 2015). "Furthermore, the siRNA-mediated knockdown of SIRT1 was performed following EV-D68 infection." (PMID 40006932, 2025). "Interestingly, though knockdown of SIRT1/3 attenuated Salmonella proliferation in macrophages, in in vivo mice model of infection, inhibition or knockdown of SIRT1/3 led to more dissemination and higher organ burden, which can be attributed to enhanced ROS and IL-6 production." (PMID 39693143, 2024). "However, contrary to the in vitro studies wherein Sirt1 or Sirt3 knockdown or inhibition resulted in attenuated intracellular proliferation, here in in vivo mouse model of infection, we observed increased bacterial organ loads owing to increased bacterial dissemination." (PMID 39693143, 2024). "However, SIRT1 expression exhibits a gradual decline at the late phase of infection." (PMID 39693143, 2024). "We first examined whether SIRT-1 colocalizes with ATG-7 during EV-D68 infection." (PMID 37850626, 2023). "Therefore, global SIRT1 inhibition may be harmful, however, transient SIRT1 inhibition immediately after vaccination or in the context of an infection appears to be safe." (PMID 34130717, 2021). "Therefore, QPRT might inhibit HCV replication through the control of NAD/Sirt1 lipogenesis required for efficient viral replication and infection." (PMID 28724915, 2017). "Indeed, LKB1 KO macrophages presented the same infection phenotype as SIRT1 KO BMMo." (PMID 25738568, 2015). "Our results first demonstrate a significant reduction in Sirt1 mRNA expression in monocytes from patients with CAP, particularly during the acute phase of the infection." (PMID 41096578, 2025).
infection (continued). "Although infection initially triggers AMPK activity due to low ATP levels, SPI2 targets the AMPK-activation complex (including Sirtuin-1 [SIRT1] and liver kinase B1) for lysosomal degradation, blunting AMPK’s role in autophagy." (PMID 40625732, 2025). "The observed upregulation of MRNIP, RAD17, and SIRT1 in the Ml group indicates an active DDR alongside mechanisms that preserve genomic integrity and immune equilibrium during infection." (PMID 41333726, 2025). "In peritoneal macrophages upon SIRT1 (EX-527-1 μM) or SIRT3 (3-TYP-1μM) chemical inhibitor treatment, an increase in IL-6 and IL-1β cytokine levels was observed at 6 hr post-infection." (PMID 39693143, 2024). "Several reports indicate the role of SIRT1 and SIRT3 in the modulation of host immune responses pertaining to infection scenarios." (PMID 39693143, 2024). "(F) Immunoblotting of host glycolytic (PGK), TCA cycle (PDHA1), and fatty acid oxidation (HADHA, ACOX-1) proteins under Sirt1 and Sirt3 knockdown condition of S. Typhimurium-infected RAW 264.7 macrophages at 16 hr post-infection." (PMID 39693143, 2024). "In confocal laser scanning microscopy (CSLM) studies, we observed a similar increase in SIRT1 and SIRT3 expression at 6 hr post-infection within the infected macrophages RAW 264.7 macrophages." (PMID 39693143, 2024). "Immunoblotting revealed increased protein expression of both SIRT1 and SIRT3 at 2 hr post-infection in comparison to the uninfected control." (PMID 39693143, 2024). "Inhibition of both SIRT1 and SIRT3 increased production of pro-inflammatory cytokine IL-6 significantly at 2 hr and 20 hr post-infection." (PMID 39693143, 2024). "In contrast, EV-D68 infection, as shown by VP3 staining, induces SIRT-1 translocation to the cytosol." (PMID 37850626, 2023). "In murine J2-macrophages, the mRNA expression levels of SIRT1, SIRT3, SIRT5, and SIRT7 were all decreased at 24 hr post-infection of TB, which was also validated using mouse bone marrow derived macrophages (BMDM)." (PMID 36993975, 2023). "Upon infection by human immunodeficiency virus 1 (HIV1), Sirt1 deacetylates the viral transactivator of transcription (Tat) protein to promote the expression of the viral genome." (PMID 37109478, 2023). "SIRT1 is the most widely studied SIRT family member in terms of the host defense and immune regulation against various infections." (PMID 36139497, 2022). "Our experiments showed that the expression of SIRT1 in the ALF model was reduced, and further decreased after the infection of F. nucleatum." (PMID 35765030, 2022). "In a macrophage model of Leishmania infantum infection, it was found that intracellular SIRT1 regulated the activation of AMPK, and the deletion of intracellular SIRT1 and AMPK in the middle and late infection stages contributes to the clearance of parasites." (PMID 36466662, 2022). "However, the IDD+NC group and IDD+SIRT1 group showed the presence of relatively high MRI signals in the vertebral bone and endplates; we deduce that there may exist some injury, inflammation, or local infection." (PMID 34987698, 2021). "While ectopic Zbtb7c repressed endogenous Sirt1 expression in NIH3T3 cells, knockdown of Zbtb7c expression by infection with recombinant adenovirus expressing shZbtb7c RNA increased endogenous Sirt1 expression." (PMID 34017061, 2021). "The greatest number of studies on the relationship between SIRT1 and HIV Tat protein concern IL-2 and NF-kB, the activity of which is crucial in the course of infection." (PMID 34685718, 2021). "Recent studies have demonstrated that SIRT1 and SIRT2 are promising antiviral targets because of their specific connection to numerous metabolic and regulatory processes affected during infection." (PMID 33669990, 2021). "However, loss of SIRT1 might lead to improved immune surveillance against pathogenic infection and nonself antigens, not all diseases benefit from the activation of SIRT1 or might even worsen Th2-mediated immune responses." (PMID 34887866, 2021).